IRF2BP1 (interferon regulatory factor 2 binding protein 1)
Description:
Acts as a transcriptional corepressor in a IRF2-dependent manner; this repression is not mediated by histone deacetylase activities. May act as an E3 ligase towards JDP2, enhancing its polyubiquitination. Represses ATF2-dependent transcriptional activation.
Synonyms: IRF-2BP1; DKFZP434M154
Tractability: PROTAC: UniProt records ubiquitination sites on it; ubiquitination databases record sites on it; its protein half-life has been measured.
Gene: Protein-coding gene on chromosome 19 (45,883,608 to 45,886,141, reverse strand). Ensembl gene ENSG00000170604.
Subcellular location: Nucleus
Subcellular location (Human Protein Atlas): Nucleoplasm
Gene Ontology:
Molecular function: protein binding; transcription corepressor activity; ubiquitin protein ligase activity
Biological process: negative regulation of transcription by RNA polymerase II; protein polyubiquitination; regulation of transcription by RNA polymerase II
Cellular component: nucleoplasm; nucleus
Genetic constraint (gnomAD): Loss-of-function variants: 9 observed, 29.21 expected, observed/expected ratio (o/e) 0.31, 90% interval 0.19 to 0.54. The synonymous counts are far from expectation, so gnomAD's model fits this gene poorly and the ratio says little. Missense variants: 631 observed, 737.69 expected, observed/expected ratio (o/e) 0.86, 90% interval 0.8 to 0.91. Synonymous variants: 416 observed, 344.52 expected, observed/expected ratio (o/e) 1.21, 90% interval 1.11 to 1.31.
Homologues: Orthologues: chimpanzee IRF2BP1 (100% identical), dog IRF2BP1 (99% identical), rat Irf2bp1 (97% identical), mouse Irf2bp1 (96% identical), zebrafish irf2bp1 (54% identical), Drosophila melanogaster Pits (31% identical), Caenorhabditis elegans ifbp-1 (22% identical), Caenorhabditis elegans ztf-11 (8% identical). Paralogues in human: IRF2BPL (51% identical), IRF2BP2 (37% identical), MYT1L (17% identical), MYT1 (16% identical), ST18 (16% identical).
Diseases named in the same sentence as IRF2BP1 in open-access papers:
IRF2BP1 is named in the same sentence as 8 diseases in open-access papers, as found by Europe PMC text mining. Sharing a sentence is not in itself a finding about the gene and the disease. The quoted sentences say what the papers report.
breast carcinoma (1 paper, 2014). "For breast cancer cells we showed that the DIF-1 complex containing the related proteins IRF-2BP1 and EAP-1 binds to the 5’-untranslated exon of the FASTKD2 gene." (PMID 25409762, 2014). "However, the DIF-1 complex does not bind to this region of the FASTKD2 gene in HeLa cells which expresses DIF-1, IRF2BP1 and EAP1 at similar levels as in breast cancer cells." (PMID 25409762, 2014). "ChIP analysis indicated that DIF-1, and its related associated proteins IRF2BP1 and EAP-1, bind to the first untranslated exon of the FASTKD2 gene in breast cancer cells while DIF-1 does not bind to the gene in HeLa cells." (PMID 25409762, 2014).
COVID-19 (1 paper, 2021). A disease caused by infection with severe acute respiratory syndrome coronavirus 2. "Of these, nine ISGs were differentially regulated in Asymptomatic versus mild COVID-19 cases; IFNAR2, IRF2BP1, IRF4, MAVS, and TRIM14 were upregulated; whilst IRF2BP2, IRF2BPL, and SOCS3 were downregulated." (PMID 34824360, 2021).
developmental delay (1 paper, 2023). "In this study, we described a patient who carry damaging de novo nonsense variant (c.136G > T;p.Glu46Ter) in IRF2BP1 and was affected with neonatal-onset microcephaly, epilepsy, hypotonia and global developmental delay." (PMID 37501076, 2023).
developmental epileptic encephalopathy (1 paper, 2023). "Among mutated genes of interest, de novo truncating variant in IRF2BP1 serves as a candidate for developmental epileptic encephalopathy." (PMID 37501076, 2023).
IRF2BP1 also shares sentences with these, for which no sentence is quoted: tumor (2 papers); epilepsy (1); microcephaly (1); neurodevelopmental disorder (1).